CD4 (CD4 molecule)
Diseases named in the same sentence as CD4 in open-access papers (continued):
Sharing a sentence is not in itself a finding about the gene and the disease.
inflammatory bowel disease (continued). "In the case of inflammatory bowel disease (IBD), approximately half of the risk SNPs (91/216) have been detected in the activated SE regions in CD4+ T cells." (PMID 32922569, 2020). "Atg16L1 mutations are associated with inflammatory bowel disease (IBD) in humans and patients with such mutations have a decreased frequency of regulatory CD4+ T cells." (PMID 30542350, 2018). "Observations in human inflammatory bowel disease support our notion, as a Th17 effector memory phenotype is dominant in the CD4+CD73+ subset of T cells found in blood and the gut." (PMID 40572025, 2025). "Nevertheless, the specific contribution of Atg7 in CD4+ T cells sensitive immune responses in inflammatory bowel disease (IBD) remains largely unclear." (PMID 40887825, 2025). "Inflammatory bowel disease (IBD) is characterized by chronic intestinal inflammation where CD4+ T lymphocytes play an essential role." (PMID 40303402, 2025). "Inflammatory bowel disease is driven by dysregulated CD4+ T cell responses to the intestinal microbiota." (PMID 41321963, 2025). "The gut microbiota-derived metabolite indole-3-propionic acid (IPA) plays an important role in maintaining intestinal mucosal homeostasis, while the molecular mechanisms underlying IPA regulation on mucosal CD4+ T cell functions in inflammatory bowel disease (IBD) remain elusive." (PMID 39956891, 2025). "Inflammatory bowel diseases (IBDs) involve chronic inflammation of the gastrointestinal tract, where effector CD4+ T-cells play a central role." (PMID 39337509, 2024). "A study led by Shanghai Jiao Tong University has shown that fungal dysbiosis plays a pivotal role in promoting inflammatory bowel disease by strengthening glutaminolysis in CD4+ T cells." (PMID 39483119, 2024). "Studies in humans with inflammatory bowel diseases suggested the anti-inflammatory function of CD8αα+CD4+TCRαβ+ IELs." (PMID 39682428, 2024). "We also observed the enrichment of Ruminococcus gnavus in PLWH with low CD4/CD8 ratio, a bacterium associated with inflammatory bowel disease and known to produce imidazole propionate." (PMID 39090139, 2024). "The expression of ETV5 in intestinal mucosa and peripheral blood CD4 T cells of inflammatory bowel disease (IBD) patients is significantly increased." (PMID 39337492, 2024). "Aberrant CD4+ T cell reactivity against intestinal microorganisms is considered to drive mucosal inflammation in inflammatory bowel diseases." (PMID 37749331, 2023). "A substantial amount of research has focused on the imbalance between Th17 and Treg cells, both of which differentiate from CD4+ T cells and contribute to inflammatory bowel disease (IBD)." (PMID 38137450, 2023). "Hookworm-derived recombinant proteins AIP-1 and AIP-2 have been shown to reduce inflammation in mouse models of inflammatory bowel disease and inflammatory airway disease by inducing CD4+Foxp3+ cells and IL-10 production." (PMID 38239430, 2023). "In CD4 + T cells of inflammatory bowel disease patients, miR-22 is upregulated and regulates inflammasome-mediated responses." (PMID 37469388, 2023). "LncITSN1-2 has been demonstrated that it promotes IBD CD4+ T cell activation, proliferation, and Th1/Th17 cell differentiation by serving as a ceRNA for IL-23R via sponging miR-125a in inflammatory bowel disease (IBD)." (PMID 35812382, 2022). "Resveratrol has also been found to inhibit CD4+ activation in vitro and in vivo, while cirsilineol, another phenolic compound, was proven to be a potential treatment for T-cell-mediated inflammatory bowel diseases due to its targeted activity on CD4+ cells." (PMID 36012942, 2022). "(J) Tregs (YFP+) from WT and Pgdfl/flFoxp3Cre mice and T effector (CD4+CD45RBhigh) cells were isolated, mixed, and transferred to Rag1-/- mice as inflammatory bowel disease (IBD) model." (PMID 34709178, 2021).
inflammatory bowel disease (continued). "In line with the reported inverse association between Se status and inflammatory bowel diseases, increasing the concentration of Se in the media generated a dose-dependent suppressive effect on IL2 production of sorted CD4 Teffs following TCR stimulation." (PMID 33851102, 2021). "Tissue-resident memory T (Trm) cells, both of the CD4 and CD8 lineage, have been implicated in disease flares in inflammatory bowel disease." (PMID 34224909, 2021). "In line with observations in NBD, a subpopulation of peripheral CD73+CD4+ T cells enriched with IL-17 cells during active inflammation was described in inflammatory bowel disease." (PMID 33719347, 2021). "Of note, DRD3-signalling in CD4+ T cells has been shown to promote inflammation in animal models of Parkinson’s disease and inflammatory bowel diseases." (PMID 34920747, 2021). "Mucosal CD4+ T lymphocytes display a potent opioid-mediated analgesic activity in interleukin (IL)-10 knockout mouse model of inflammatory bowel diseases (IBD)." (PMID 34299013, 2021). "Previously, increased levels of CD4+ T cells-derived IL-2 and IL-21 have been reported in inflammatory bowel disease." (PMID 31936604, 2020). "Among cases with intestinal histopathology performed, 1 heterogeneous case was diagnosed as inflammatory bowel disease and 3 CD4+ T‐cell cases were diagnosed as intestinal lymphoma." (PMID 31693230, 2020). "In contrast, intestinal regulatory B cells and circulating regulatory CD4+/CD8+ T cells produced high level of IL-35 in active inflammatory bowel disease." (PMID 32276581, 2020). "Using the 2 μg dose of 89Zr-cDb, CD4 T cells were monitored in a mouse model of inflammatory bowel disease." (PMID 32582173, 2020). "MYD88 has been shown to be important for regulation of CD4+ T cells, including in promoting activation in the murine inflammatory bowel disease model." (PMID 32119719, 2020). "TRIM21 also influences T cell differentiation by targeting IRF3 to inhibit ex vivo Th1 and Th17 differentiation in CD4+ T cells isolated from inflammatory bowel disease (IBD) patients." (PMID 30741923, 2019). "It is known that CD4+ ROR-γt+ cells are involved in the pathology of inflammatory bowel diseases such as ulcerative colitis and Crohn’s disease." (PMID 31921383, 2019). "Inhibition of ROCK2 remarkably decreases the percentage of IFN-γ+CD4+T cells and IL-17A+CD4+T cells, and increases the percentage of Foxp3+CD4+T cells in inflammatory bowel disease." (PMID 31655796, 2019). "Previous studies with CD4-Cre-Il10fl/fl mice showed the spontaneous onset of inflammatory bowel disease (IBD) as mice aged, suggesting the crucial role of T cell-derived IL-10 in protecting mice from excessive inflammation." (PMID 31803193, 2019). "In this model, functional Treg cells prevent the development of inflammatory bowel disease (IBD) characterized by the differentiation of naive CD4+ T cells into Th1 and Th17 cells and lymphocytic inflammation of the large intestine." (PMID 30862784, 2019). "We investigated the effects of BBR on the mechanisms of mucosal CD4+T cell activation in vitro and on the inflammatory responses in T cell transfer mouse models of inflammatory bowel disease (IBD)." (PMID 31417110, 2019). "Yet, CD4+ T cells are also known to be the main drivers of inflammatory bowel disease (IBD) when this balance is perturbed." (PMID 29910812, 2018). "For example, the colons of mice lacking BCL11B display significant levels of infiltrated proinflammatory T helper type 1 (Th1) and Th17 CD4+ T cells, neutrophils and macrophages and develop inflammatory bowel disease." (PMID 30089823, 2018). "Sema3A expression levels in CD4+/CD25+ T cells were significantly lower in patients with inflammatory bowel diseases than in controls, although their serum Sema3A levels were significantly higher." (PMID 30538782, 2018). "This article describes the CD4+ T cell populations of the BM and reviews their role as osteoclastogenic population in inflammatory bowel disease." (PMID 26734007, 2015).
inflammatory bowel disease (continued). "In a model of inflammatory bowel disease, CD4 T cells strongly expressed the IL-22 reporter in mesenteric lymph node." (PMID 26834739, 2015). "Here we report two murine models of inflammatory bowel disease: RAG-2−/− mice adoptively transferred with CD4+CD45RBhigh T cells; and IL-10−/− mice, accompanied by the infiltration of mononuclear cells in the liver." (PMID 24392145, 2014). "CD4+ T cells play a central role in the development of inflammatory bowel disease (IBD) via high-level production of effector cytokines such as IFN-γ and TNF-α." (PMID 23840334, 2013). "Here, we aimed to investigate the role of CD69 in accumulation of CD4 T cells in intestine using murine models of inflammatory bowel disease." (PMID 23776480, 2013). "PGE2 increased the numbers of CD4+IL-17A+ T cells and neutrophils in the colonic tissue in a mouse model of experimental inflammatory bowel disease." (PMID 22590492, 2012). "Patients suffering from inflammatory bowel disease have an increased number of lamina propria CD4+CD25high cells in inflamed tissue compared with control patients, although it is not sufficient to dampen inflammation." (PMID 22254115, 2011). "There was a difference in the frequency of CD4 cells in the inflammatory bowel disease control cohort (mesenteric lymph nodes from healthy controls were unavailable)." (PMID 21864372, 2011). "Furthermore, 89Zr-GK1.5 cDb was successfully used to visualize the reconstitution of CD4+ T cells after hematopoietic stem cell transplantation and in a model of inflammatory bowel disease." (PMID 40775564, 2025). "Also, Lactobacillus reuteri is able to alter CD4+ T cells into CD4 + CD8αα + double-positive intraepithelial lymphocytes that alleviate inflammatory bowel disease." (PMID 39767682, 2024). "Similarly, the populations of IL-21–, IFN-γ–, and IL-17–producing CD4+ T cells are increased in patients with inflammatory bowel disease (IBD), including both CD and ulcerative colitis, compared with healthy controls." (PMID 35503415, 2022). "Moreover, it is unclear how cytotoxic CD4 T cells change in patients with inflammatory bowel disease (IBD)." (PMID 36353619, 2022). "Adoptive transfer of naïve CD4+ T cells from syngeneic mice into immunodeficient mice induces chronic colitis, similar to inflammatory bowel diseases (IBD) in humans, due to differentiation of T cells into pathogenic Th1 and Th17 cells in the absence of regulatory T cells (Tregs)." (PMID 35990633, 2022). "Furthermore, in vitro investigations presented that HDAC4 negatively regulated the polarization of Th17 cells in naïve CD4+ T cells of patients with AS, which was in line with a previous study focusing on inflammatory bowel disease." (PMID 35602496, 2022). "Relying on competing with Wnt ligands for LRP5/6 receptors, DKK1 has a role in promoting the development and differentiation of immunocytes, such as macrophages, DCs, and CD4+ T cells, which actively participates in the progression of inflammatory bowel disease." (PMID 34090510, 2021). "For example, the transfer of CD4+CD25+ Tregs into mice with established inflammatory bowel disease, induced by injecting CD4+CD45RBhigh T cells into severe combined immunodeficiency (SCID) mice, relieved wasting disease symptoms as well as infiltration of inflammatory cells." (PMID 32983168, 2020). "CD4+ T cell imaging may be of clinical value for immune-driven pathologies such as inflammatory bowel disease and multiple sclerosis." (PMID 32582173, 2020). "Our study thus implicates Fas in CD4+ T cells as a target for inflammatory bowel disease therapy." (PMID 31266950, 2019). "Evidence arising from experimental models of inflammatory bowel disease suggests that CD4+ T cells are key players in the initiation and regulation of the immunopathologic processes, partly through production of proinflammatory cytokines such as tumor necrosis factor-α (TNF-α)." (PMID 30483153, 2018).
inflammatory bowel disease (continued). "Additionally, the administration of probiotics in different animal models improved inflammatory bowel disease, atopic dermatitis, and RA, probably as a result of enrichment of CD4+Foxp3+ Tregs in inflamed body areas." (PMID 27553386, 2016). "Interestingly, IL-17-producing Foxp3+CD4+ lymphocytes are also observed in inflammatory bowel disease (IBD) patients." (PMID 26734006, 2015). "Importantly, increased accumulation of CD4+ T cells in the intestine is a key feature of inflammatory bowel disease and presents an important therapeutic target." (PMID 25944983, 2015). "Since intestinal mucosal CD4+ T cells are being increasingly studied under disease conditions (e.g. inflammatory bowel disease and HIV), it is important to rigorously investigate the baseline mucosal immune environment throughout the gut in healthy individuals." (PMID 22829946, 2012). "Finally, a model of inflammatory bowel disease (IBD) was used as an in vivo assay of Treg function: upon adoptive co-transfer of CD4+CD25+ T cells in SCID mouse, the onset of IBD was abrogated and colitogenic Teff cells were shown to undergo apoptosis." (PMID 22973270, 2012). "Besides the induction of IL-10-producing CD8+ Treg, ZPS also induces immunosuppressive CD4+ Treg, which produce IL-10 and prevent pathological conditions such as inflammatory bowel disease (IBD) and experimental autoimmune encephalomyelitis (EAE)." (PMID 21234388, 2010). "Studies have also shown that patients with inflammatory bowel disease (IBD) have a large accumulation of CD4+ T cells in the intestinal tract." (PMID 40746956, 2025). "CEACAM5 expressed on intestinal epithelial cells (IECs) can bind with CD8α on CD8+ suppressor T cells, leading to the inhibition of CD8+ suppressor T cell activation and the increasing proliferation of CD4+ T cells in inflammatory bowel disease (IBD) patients." (PMID 38686388, 2024). "These LPAM1+ (α4β7 integrin) CD4+ T cells are critical for the initiation and development of inflammatory bowel disease (IBD) and are being targeted by monoclonal antibodies etrolizumab (β7) and natalizumab (α4)." (PMID 38743922, 2024). "Additionally, miR-22 is upregulated in CD4 + T cells of patients with inflammatory bowel disease." (PMID 37469388, 2023). "More recently, a mechanistic study in mice revealed that perturbations in Hdac7 function can contribute to autoimmunity and a phenotype resembling inflammatory bowel disease (IBD) by altering CD4/CD8 DP thymocyte and iNKT cell development." (PMID 35303381, 2023). "To infer potential mechanisms driving disease subtypes among patients with inflammatory bowel disease (IBD), we profiled the transcriptome of purified circulating monocytes and CD4 T-cells." (PMID 36746519, 2023). "Regulatory T-cell populations, including Tr1s, are depleted in inflammatory bowel disease (IBD), while inflammatory and cytotoxic CD4+ T-cells are relatively overrepresented." (PMID 37654482, 2023). "Grievously, inflammatory bowel diseases (IBD) trigger an exaggerated and uncontrolled immune response against normal microbiota activating CD4(+) T helper (Th) cells." (PMID 36831029, 2023). "In the case of inflammatory bowel disease (IBD), CD4+ T cells, dendritic cells and eosinophils have been identified as the primary sources of IL-22BP." (PMID 37324022, 2023). "The inflamed mucosa of inflammatory bowel disease (IBD) patients shows increased enrichment of CD4+CXCR3+ T cells." (PMID 35813827, 2022). "In contrast, Kang and coworkers observed in a mouse model of Crohn’s disease that VAD decreased the homing of CD4+ T cells to the gut, which is beneficial during intestinal inflammation in inflammatory bowel disease (IBD)." (PMID 36501067, 2022). "Moreover, lnc-ITSN1-2 may promote the differentiation of T helper type 1 (Th1) and Th17 cells in CD4+ T cells of inflammatory bowel disease (IBD) via regulating the microRNA (miR)-125a/interleukin (IL)-23R axis." (PMID 34406596, 2021).
inflammatory bowel disease (continued). "Subsequently, CD4+IL-10+ T cells were shown to exert immunosuppressive effects in various disease models, such as inflammatory bowel disease (IBD) and experimental autoimmune encephalomyelitis (EAE)." (PMID 34187557, 2021). "Thus, our results suggest that upregulation of miR-10a-5p by UA restrains SOCE in murine CD4+ T cells and UA could be used as a natural immune-suppressant during various inflammatory disorders including inflammatory bowel disease." (PMID 31417547, 2019). "For example, polysaccharide A, produced by B. fragilis, prevents inflammatory bowel disease (IBD) via an IL-10-producing CD4+ T cell-dependent mechanism." (PMID 31921196, 2019). "Here we investigate how a pleiotropic cytokine interleukin (IL)-15 may modify the functional commitment of CD4+ T cells expressing the lineage-associated transcription factors: forkhead box P3 (Foxp3; Treg) and RORγt (Th17) in the context of inflammatory bowel disease (IBD)." (PMID 26964669, 2016). "Altered % of Tregs expressing sema3A in patients with inflammatory bowel diseases (IBD) is partially responsible for their failure in preventing CD4+ effector T cell induced inflammation in IBD in peripheral blood." (PMID 25978359, 2015). "This mutation was associated with a high incidence of inflammatory bowel disease (IBD), skewed cytokine profile of effector T cells towards Th2/Th17 and inefficient natural regulatory CD4 T lymphocytes (Treg)." (PMID 22275874, 2012). "The dysregulation of the immune response between microbial-derived antigens and the immune response to pathogens in the gut can lead to human inflammatory bowel disease (IBD), which is partly characterized by an abnormal CD4+ T-cell response." (PMID 39747850, 2025). "These miRNAs have been studied in CD4+ T cells, but minimally in the effector roles of CD8+ T lymphocytes in inflammatory bowel disease, though increasingly, evidence suggests that miR‐29a/b have a significant regulatory role in CD8+ T cells' memory capacity." (PMID 40873647, 2025). "In case of inflammatory bowel disease, BBR is known to induce protective immune responses by modulating IFNγ and IL17 CD4+ T cells by activation of AMP kinase." (PMID 36881595, 2023). "Despite the elevated pool of T lymphocytes in the mucosa of patients with inflammatory bowel disease (IBD), the active disease associates with diminished anti-inflammatory forkhead box P3 CD4-positive regulatory T cells (FOXP3+CD4+ Tregs) in the peripheral blood." (PMID 36140736, 2022). "Intestinal CD4+ T cells are essential mediators of immune homeostasis and inflammation and are believed to be key players in the pathogenesis of inflammatory bowel disease (IBD)." (PMID 35468944, 2022). "In the gut inflammation in inflammatory bowel diseases (IBD), IL-9-producing CD4+ T cells were found to be colitogenic, as gut epithelial cells of ulcerative colitis patients expressed elevated levels of IL-9R." (PMID 29867972, 2018). "Periphery CD4 T cells of HDAC3 knockout mice were skewed toward RORgammat(+) IL-17-producing Th17 cells, leading to inflammatory bowel disease." (PMID 30402512, 2018). "Ectopic expression of FOXP3 in CD4+CD25− T cells may endow CD4+CD25− T cells with Treg-like suppressive capability to prevent inflammatory bowel disease (IBD) and autoimmune gastritis." (PMID 26441996, 2015). "In fact, patients with inflammatory bowel disease exhibit higher prevalence of circulating IL-17 and FOPX3 double positive CD4+ T cells." (PMID 26441347, 2015). "Here we show that CD4+Foxp3+Tregs produce the effector cytokine IL-17A during oropharyngeal candidiasis (OPC) and inflammatory bowel disease in a TLR-2/Myd88 signaling dependent manner." (PMID 25790134, 2015). "Immune responses against intestinal microbiota contribute to the pathogenesis of inflammatory bowel diseases (IBD) and involve CD4+ T cells, which are activated by major histocompatibility complex class II (MHCII) molecules on antigen-presenting cells (APCs)." (PMID 24489792, 2014).